LEP (leptin)
Diseases named in the same sentence as LEP in open-access papers (continued):
Sharing a sentence is not in itself a finding about the gene and the disease.
Insulin resistance (continued). "Aged mice exhibited impaired glucose tolerance and insulin resistance and showed higher serum levels of insulin and leptin and lower levels of adiponectin." (PMID 34143796, 2021). "CR improved glucose tolerance and insulin resistance, lowered baseline serum insulin and leptin levels, and increased serum adiponectin levels." (PMID 34143796, 2021). "Adiponectin was reported helpful to improve insulin sensitivity and correct disturbances in whole-body glucose homeostasis induced by a high-fat diet, but leptin increases insulin resistance under a high-fat diet." (PMID 33672704, 2021). "Decreased leptin concentrations in serum in obese patients significantly protect those patients from developing insulin resistance, T2D, cardiovascular and autoimmune diseases." (PMID 33369170, 2021). "Insulin resistance and elevated serum leptin levels were interrelated and jointly promoted lung cancerization." (PMID 33777737, 2021). "Visceral fat accumulation caused by inflammatory cytokines and tumor necrotizing factor-alpha interrupts both insulin resistance and the leptin level." (PMID 34948754, 2021). "Many studies have shown adipokines (leptin, adiponectin, resistin, etc.)play an important role in insulin resistance and T2D development." (PMID 33478575, 2021). "The central function of leptin is to inhibit food intake and appetite, and the peripheral effects are mainly related to insulin resistance, inflammatory response, oxidative stress, atherosclerosis." (PMID 34093426, 2021). "Leptin, due to its direct relationship with body fat levels and insulin resistance, has been shown to be an independent predictor of the presence or development of NAFLD." (PMID 34209386, 2021). "The purpose of this review is to offer a comprehensive view of the complex interplay between leptin and the central nervous system, providing further insights on the impact of autonomic nervous system balance on adipose tissue and insulin-resistance." (PMID 34068919, 2021). "The CGL patients showed low fasting levels of leptin and adiponectin, dyslipidemia, and insulin resistance." (PMID 33411809, 2021). "This leads to a number of issues including weight gain, worsened insulin resistance, increased levels of leptin, and decreased levels of adiponectin." (PMID 33531076, 2021). "Insulin therapy normalized Leptin and adiponectin receptor levels in these patients, which had prevented insulin resistance and effectively controlled the appetite and weight of obese patients." (PMID 34904015, 2021). "Leptin decreases fat accumulation in the liver and generally functions to improve insulin sensitivity, but promotes insulin resistance during leptin resistance states." (PMID 36994336, 2021). "Leptin plays a vital role in the central regulation of food intake and energy expenditure, as well as glucose metabolism, which makes leptin an important adipose-derived hormone in promoting insulin resistance." (PMID 34122341, 2021). "Glucose, HbA1c, triglyceride, low density cholesterol (LDL), leptin, and Homeostatic Model Assessment for insulin resistance (HOMA-IR) levels increased and insulin and HOMA-β levels decreased in the diabetic rats compared to the healthy control group." (PMID 33641315, 2021). "Metabolic improvements in both groups were also observed for insulin resistance, leptin, plasminogen activator inhibitor-1, and resistin." (PMID 34501456, 2021). "Tzanela and colleagues showed that leptin levels are higher at the onset of sepsis and they correlate with insulin levels and insulin resistance." (PMID 33907162, 2021). "Decreased circulating levels of serum insulin and leptin also supported the improved insulin resistance in Tg mice." (PMID 33856409, 2021). "Induces glucose intolerance, insulin resistance, hepatic steatosis/steatohepatitis, increased leptin levels, increased cholesterol, and white adipose tissue disfunction." (PMID 34899613, 2021).
Insulin resistance (continued). "Male rats with T2DM had an increase in the body weight, the increased levels of glucose, glycated hemoglobin (HbA1c), insulin, leptin, triglycerides and total cholesterol, and an increase in the insulin resistance index." (PMID 35008624, 2021). "In general, large adipocytes, usually observed in obese WAT, accumulate more TG in unilocular lipid droplets and secrete less adiponectin and more leptin and inflammatory cytokines, which leads to inflammation, insulin resistance, and leptin resistance." (PMID 33799894, 2021). "AT is responsible for the synthesis and secretion of several hormones including leptin, adiponectin, visfatin, or angiotenstin, which modulates insulin resistance and inflammatory axis." (PMID 33536069, 2021). "Secondly, we were unable to examine metabolic and nutritional profiles such as serum cytokines, nutrients, leptin, and insulin resistance because of the retrospective nature of this work." (PMID 34901116, 2021). "Mean leptin and insulin resistance in the digital CBT group at 8 weeks was significantly reduced compared to the control group (–15.8%, SD 29.9, vs 7.2%, SD 35.9, P=.01; and –7.1%, SD 35.1, vs 14.4%, SD 41.2, P=.04)." (PMID 32352391, 2020). "SOCS3 is a key regulator of the JAK-STAT pathway, and studies have shown that SOCS3 plays a key role in leptin and insulin resistance." (PMID 32168898, 2020). "These obese nude mice demonstrated an altered metabolism milieu such as hyperglycemia, hyperinsulinemia, and insulin resistance and had a higher serum level of leptin and visfatin than lean mice by the end of the animal experiment." (PMID 33381605, 2020). "Because ob/ob mice lack functional leptin, they develop severe insulin resistance with hyperglycemia and hyperinsulinemia and are described as a model for the prediabetic state." (PMID 33167521, 2020). "Logistic regression analysis identified leptin and triglycerides as independent predictors of insulin resistance (OR 1.247, 95% CI 1.076–1.447, p = 0.003; OR 0.357, 95% CI 0.137–0.917, p = 0.032)." (PMID 32092909, 2020). "Inflammatory substances undergo a vicious cycle that causes the relapse of metabolic abnormalities, again through insulin resistance and leptin disruptions." (PMID 32471118, 2020). "In cancer patients, sarcopenia has been of pro-inflammatory cytokines and leptin, which influence insulin resistance and energetic metabolism." (PMID 33327483, 2020). "In T2DM, dysregulation of the leptin-induced JAK–STAT signalling pathway is thought to play a key role in insulin resistance." (PMID 32914050, 2020). "Little is known about the jejunal insulin signalling pathways in insulin resistance/diabetes states and their possible regulation by insulin/leptin." (PMID 31936857, 2020). "The developmental mechanism of nonalcoholic fatty liver disease (NAFLD) is considered to be primarily related to insulin resistance via the roles of inflammatory cytokines and adipocytokines (e.g., adiponectin and leptin)." (PMID 32492866, 2020). "The GEE test results reveal that the leptin serum levels and insulin resistance are approximately 17 ng/mL and 2 units lower in men than women, respectively." (PMID 33680012, 2020). "In order to understand the mechanism of cooperation between galanin and leptin in amelioration of insulin resistance, we surveyed Akt phosphorylation, a key link of signalling systems of both hormones." (PMID 32395890, 2020). "Insulin resistance and leptin act to reduce food intake and to increase energy expenditure through the action on the hypothalamic neurons, for which they are named “signals of body adiposity”." (PMID 32694929, 2020). "Some studies indicate that high concentrations of leptin, the first adipocytokine to be identified, positively correlate with insulin resistance, T2D, and cardiovascular diseases." (PMID 33324342, 2020).
Insulin resistance (continued). "In terms of experimental studies, clinical trials in obese individuals with type 2 diabetes found that leptin therapy was ineffective in improving type 2 diabetes and insulin resistance." (PMID 32131811, 2020). "In men, increased leptin levels are a predictor for developing diabetes independently of basal adiposity, insulin resistance, glucose or age27." (PMID 32170116, 2020). "Maternal pre-pregnancy BMI, GWG, insulin resistance, inflammation, and glucose, lipid, leptin, and amino acid concentrations have both independent and interacting effects on fetal growth, operating both early and late in pregnancy." (PMID 33142800, 2020). "Higher levels of ceramides correlate with low levels of adiponectin as well as with leptin and insulin resistance, indicating that these sphingolipids contribute to dysfunction in cardiovascular, hepatic, and adipose tissue." (PMID 33133017, 2020). "Hyperglycemic and glucose intolerance; reduced islet insulin content and elevated proinsulin levels; increased epididymal fat mass and leptin levels; reduced glucose production, and insulin resistance at later ages, leading to complete onset of diabetes." (PMID 33193056, 2020). "Elevated levels of HDL, leptin, adiponectin, glutathione-conjugate, phytosphingosine and lysophospholipids appear to protect young women from insulin resistance." (PMID 31941993, 2020). "Besides, deteriorated metabolic status influences elevated levels of inflammatory cytokines such as interleukin 6 (IL-6), tumor necrosis factor alpha (TNF-α), C-reactive protein (CRP), and leptin hormone, which may be implicated in insulin resistance and tumor development." (PMID 33238496, 2020). "An increase in this ratio is better correlated with reduced insulin resistance than leptin or adiponectin alone." (PMID 33158191, 2020). "We concluded that increased irisin and leptin levels can predict the insulin resistance in obese patients." (PMID 32544194, 2020). "In summary, the results of our present study showed that the central effect of galanin and leptin on appetite and bodyweight of animals is opposite, but that on amelioration of insulin resistance is cooperative." (PMID 32395890, 2020). "Different pathogenic mechanisms have been suggested as contributing to the higher incidence of sleep breathing disorders among patients with type 2 diabetes: insulin resistance, leptin resistance, systemic inflammation and autonomic or peripheral neuropathy." (PMID 32260419, 2020). "Serum concentrations of leptin and total ghrelin were measured and homeostasis model assessment of insulin resistance (HOMA-IR) was calculated." (PMID 32927680, 2020). "As leptin has a direct effect on insulin sensitivity, leptin replacement therapy was proposed as a novel therapeutic option in metabolic disorders, including insulin resistance and T2DM." (PMID 32655492, 2020). "Leptin corrects insulin resistance and hyperglycemia in patients with hypoleptinemia and lipodystrophy and in patients presenting with a combination of lipodystrophy and type 1 diabetes." (PMID 31743040, 2020). "It is known that adipose tissue increases the secretion of proinflammatory cytokines, such as IL-6, TNF-α, and leptin, which are closely related to the development of insulin resistance." (PMID 32694929, 2020). "In the present study, leptin levels were significantly and positively correlated with BMI, waist circumference, high blood pressure, and insulin resistance and inflammatory marker levels." (PMID 31914480, 2020). "This organ releases the adipocyte-derived hormones leptin, adiponectin, and resistin, which have important roles in metabolic pathological processes and insulin resistance." (PMID 33086618, 2020). "Both doses of the MTHF diets led to 8% higher food intake and associated with lower plasma leptin at parturition, but higher leptin at 19-weeks and insulin resistance at 1-week post-weaning." (PMID 33375730, 2020).
Insulin resistance (continued). "This positive energy balance can directly contribute to the excess of body fat percentage (BF%) and, consequently, to an increase in blood pressure, triglycerides, free fatty acids, leptin production, dyslipidemias, hyperuricemia, and insulin resistance." (PMID 32694929, 2020). "In the Brazilian study, higher leptin levels were positively correlated with insulin resistance (HOMA‐IR index) in children and adolescents (Gonzaga, Medeiros, de Carvalho, & Alves, 2014)." (PMID 31914480, 2020). "Insulin resistance has long been known to significantly increase the leptin production in adipocytes." (PMID 31929574, 2020). "The underlying basis for hyperphagia and excess weight gain in these models included disrupted leptin responsiveness, hyperinsulinemia, insulin resistance, and reduced satiety resulting in increased meal size." (PMID 32326226, 2020). "The homeostasis model assessment 2 model was used to determine the insulin resistance index, and fasting adiponectin, leptin, insulin, c-peptide, glucose, HbA1c, and lipid profiles were analysed." (PMID 32092909, 2020). "Although the mechanisms are not yet well-established, studies have shown a relationship between insulin resistance and increased serum levels of leptin." (PMID 33115462, 2020). "On the other hand, lower birth size in combination with faster body weight gain during 0.5–1 year predicted higher adiposity, leptin, and insulin resistance in mid-childhood." (PMID 33114326, 2020). "In contrast, C57BL/6J A-ZIP (lipodystrophic) mice have been previously reported to show reduced adipose tissue mass, low leptin levels and very prominent hepatic steatosis with only mild insulin resistance and normoglycemia." (PMID 32452759, 2020). "Several studies have demonstrated the correlation of leptin with metabolic syndrome, including visceral obesity, hypertension, insulin resistance, and dyslipidemia." (PMID 31914480, 2020). "The lack of adipose tissue in these individuals results in lipotoxicity-induced insulin resistance and low levels of leptin (fasting leptin concentration of less than 4 ng/ml)." (PMID 32131811, 2020). "Significant differences were found between groups regarding sVCAM1 (p = 0.0134), leptin (p = 0.0265), and all insulin resistance scores." (PMID 32858998, 2020). "Vitis vinifera L. grape skin extract prohibited body weight gain, insulin resistance and dyslipidemia, and maintained the leptin and adiponectin levels in plasma and adipose tissue." (PMID 32466434, 2020). "Our results indicate that leptin resistance, as indicated by elevated leptin levels, can be regarded as a contributing factor to insulin resistance in cirrhotic patients, whereas triglycerides elicited a weak protective effect." (PMID 32092909, 2020). "Insulin resistance in lipoatrophic mice was completely reversed by combining doses of adiponectin and leptin but was only partially reversed by either adiponectin or leptin alone." (PMID 32131811, 2020). "In hypertensive insulin-resistant men, fasting plasma leptin levels were higher than in controls and correlated with increased myocardial wall thickness." (PMID 32655492, 2020). "The multiple linear regression models found that the behavioral variables, BF%, insulin resistance, and hs-CRP were linearly associated with the inflammatory biomarkers TNF-α, IL-6, and leptin." (PMID 32694929, 2020). "Significant differences were found between the groups regarding sVCAM1 (p = 0.0134), leptin (p = 0.0265) and all insulin resistance scores, with differences influenced by the subjects’ gender." (PMID 32858998, 2020). "Morbidly obese subjects have increased levels of leptin and inflammatory markers, decreased levels of adiponectin, an increase of insulin resistance, and an increased level of SR expression in mature adipocytes." (PMID 32244787, 2020).
Insulin resistance (continued). "Serum leptin levels (51.24 ± 18.12 vs. 9.10 ± 2.99: p-value, < 0.0001), serum cholesterol levels (198.2 ± 32.1 vs. 151.2 ± 21.2, p-value < 0.0001) and insulin resistance (7.9 ± 2.1 vs. 6.3 ± 1.9, p-value < 0.0001) were higher in obese patients." (PMID 33489589, 2020). "SGA/IUGR twins demonstrate relative insulin resistance accompanied by decreased fetal and increased placental leptin signaling." (PMID 32778645, 2020). "Our results indicate that elevated leptin, a marker of leptin resistance, can be regarded as an important contributing factor of insulin resistance in cirrhotic patients." (PMID 32092909, 2020). "The oral administration of Ga caused dose-dependent decreases in metabolic parameters including hepatic TG contents, hyperglycemia with insulin resistance, and blood levels of insulin and leptin." (PMID 32792584, 2020). "Açaí reduced blood glucose, insulin resistance, leptin and IL-6 levels, lipid profile, and vascular dysfunction." (PMID 32565751, 2020). "After treatment, leptin, adiponectin, and vitamin D levels show significant differences compared to the baseline values (P < 0.05) but there isn’t any significant change in insulin resistance (P = 0.36)." (PMID 33680012, 2020). "For example, a high-fat diet of fathers in the time of conception is related to an impaired glucose metabolism, insulin resistance, weight gain, elevated triglyceride and increased leptin levels in the following generation." (PMID 33382823, 2020). "Circulating leptin level was positively correlated with inflammatory, insulin resistance markers, and visceral obesity markers in all subjects." (PMID 31914480, 2020). "This abnormal high level of maternal leptin is also positively correlated with maternal insulin resistance, and offspring exposed to maternal obesity and/or gestational diabetes mellitus are either growth restricted, normal, or overweight." (PMID 33114326, 2020). "Leptin levels correlated with insulin resistance index (IRI) (ρ = 0.484, p < 0.001), BMI (ρ = 0.347, p < 0.001) and insulin concentrations (ρ = 0.336, p < 0.001)." (PMID 32092909, 2020). "In this study, serum resistin, leptin, and TNF-α levels were dramatically decreased by Pt-PS supplementation, which was associated with the alleviation of insulin resistance." (PMID 32971772, 2020). "A lot of endocrine hormones, including galanin and leptin, are involved in the pathogenesis of insulin resistance for their multiple effects on glucose and lipid metabolism." (PMID 32395890, 2020). "The purpose of current study was to investigate the combined effect of central leptin and galanin on insulin resistance in adipose cells." (PMID 32395890, 2020). "Among the best characterized activators of JAK signaling in the context of metabolic disorders, certain adipokines, including leptin and resistin, are known to be involved in the pathogenesis of insulin resistance." (PMID 32413585, 2020). "Here, we investigated therapeutic potential of hesperidin to improve leptin and insulin resistance using high fat diet (HFD)-induced obese experimental animal model." (PMID 31929574, 2020). "This emerging biomarker correlates with insulin resistance better than adiponectin or leptin alone, while insulin resistance correlates with cognitive dysfunction." (PMID 32326613, 2020). "In the case of HFD-induced obese mice with insulin resistance, fatty acid oxidation is increased in a leptin-dependent manner, and TCA cycle activity is enhanced." (PMID 32616893, 2020). "Leptin, adiponectin, vitamin D levels, and insulin resistance, before and after vitamin D supplementation (The Wilcoxon matched-pairs signed-rank test)." (PMID 33680012, 2020). "The resultant increased appetite further perpetuates the leptin and insulin resistance and IL-6 mediated inflammation." (PMID 33202598, 2020).